INS (insulin)
Diseases named in the same sentence as INS in open-access papers (continued):
Sharing a sentence is not in itself a finding about the gene and the disease.
diabetes (continued). "An institutional-based cross-sectional study was conducted among diabetes patients on insulin therapy from May to June 2022." (PMID 37143082, 2023). "Hypertension, impaired metabolism of insulin, overweight, and changes in lipids profiles in patients with SUD under MMT can result in the risk of drug‐related mortality, metabolic abnormalities, infectious complications, pulmonary diseases, and diabetes." (PMID 36448959, 2023). "Patients with type 1 diabetes mellitus may intentionally reduce or omit doses of insulin to lose weight." (PMID 36793059, 2023). "Авторами был произведен электронный поиск публикаций в базах данных PubMed/MEDLINE и Google Scholar с использованием ключевых слов “amyloid beta”, “Alzheimer type-3-diabetes”, “intranasal insulin”, “metformin”, “type 2 diabetes mellitus”, “incretins” и “PPARγ agonists”." (PMID 37968954, 2023). "Diabetes is characterized by elevated blood sugar and insulin resistance." (PMID 37720287, 2023). "Disruptions to this tightly orchestrated glucoregulatory system can lead to hyperglycaemia and the metabolic disorder of diabetes, which include decreased glucose usage, increased glucose production, a failure to secrete sufficient quantities of insulin, and insulin resistance." (PMID 37311878, 2023). "The participants in cluster 2 who developed diabetes showed significant increases in insulin resistance (from 0.84 ± 0.20 to 1.18 ± 0.49, p < 0.001), along with a modest decrease in insulin secretion (from 72.9 ± 17.4 to 64.6 ± 18.8, p = 0.005) during the 5-year follow-up period." (PMID 36769457, 2023). "Higher magnesium intakes were associated with lower fasting insulin levels in healthy women without diabetes." (PMID 37185729, 2023). "Regulating the insulin signal and enhancing the expression of GLUTs could be a novel strategy for reversing cognitive dysfunction in diabetes." (PMID 37396164, 2023). "The single method for diabetes patients to tolerate DD is to maintain their blood sugar at normal levels, which can only be managed if the used treatment entails the appropriate diet, taking oral diabetes treatment or some kind of insulin, and practicing suitable exercises." (PMID 37238305, 2023). "Diabetes mellitus (DM) is a chronic metabolic disease that is characterized by an elevated level of blood glucose resulting from defects in insulin secretion, resistance to insulin action, or both." (PMID 36979643, 2023). "The restoration of insulin signaling as a treatment for diabetes is a beneficial NASH treatment." (PMID 37408268, 2023). "In a systematic review and meta-analysis, we conducted of 10 studies of insulin education delivered by diabetes specialists in primary care/outpatient settings; there was a statistically significant improvement in glycaemic control for intervention participants." (PMID 37237318, 2023). "Their ages ranged from 3 to 71 years (51 males and 56 females) with median (IQR) diabetes duration 5 (1.5–10) years; 79 (73.8%) patients used multiple daily injections and 28 (26.2%) patients used open loop insulin pump (sensor augmented pump-predictive low glucose management [SAP-PLGM])." (PMID 37845757, 2023). "Insulin remains a central treatment modality in the management of diabetes." (PMID 37971985, 2023). "Future research in terms of refinement and further testing of DIME will need to consider the views of people with T2D who need insulin, the friends/relatives and carers who support them and the diabetes health professionals currently delivering insulin education." (PMID 37237318, 2023). "Ten patients were affected by diabetes and treated with metformin, only two patients with associated insulin, none with SGLT2i or GLP-1." (PMID 37887378, 2023). "Due to cost, around 14%-20% of individuals with diabetes report lowering or postponing treatment; rates may exceed 25% among persons with diabetes who are taking insulin." (PMID 37264625, 2023).
diabetes (continued). "Therefore, in adults, negative islet autoantibodies should prompt consideration of other diabetes subtypes, and potentially the trial of non-insulin treatment and insulin cessation." (PMID 37728732, 2023). "However, there was an unexpectedly large proportion of respondents who reported taking insulin therapy to manage their GDM compared to the 2019 National Diabetes Service Scheme (NDSS) data (33.8% vs. 46.2% for NDSS data and study respondents, respectively)." (PMID 36771195, 2023). "The intake of food containing resistant starch could help control diabetes by reducing blood glucose and increasing insulin sensitivity and intestinal hormones." (PMID 37238887, 2023). "Restrictions to inclusion criteria in the papers reviewed were based on multiple factors: duration of diagnosis, being non-insulin taking and/or naïve to glucose lowering medication, age, existing diabetes complications, existing mental health diagnosis, BMI and HbA1c level." (PMID 37972024, 2023). "Interestingly, it was noted that maternal insulin therapy seemed to reverse the adverse effects of maternal diabetes, and male and female offspring reacted differently to the exposure to hyperglycemia, with male offspring demonstrating worse outcomes." (PMID 37469977, 2023). "With the increase of microalbuminuria, the subjects had a longer course of diabetes, a higher proportion of hypertension history, a higher rate of insulin use, and the level of FIns, SBP, HOMA-β, BUN, and creatinine was gradually increased, while eGFR gradually decreased." (PMID 37091044, 2023). "While all children with CAs were not at increased risk of diabetes requiring insulin therapy, children with specific chromosomal anomalies, particularly children with Down syndrome and CHD, had an increased risk." (PMID 36869270, 2023). "Additionally, a greater number of multimorbid patients with diabetes were being treated with dietary control (p = 0.024) and insulin (p = 0.012) compared with the diabetes only group." (PMID 37081950, 2023). "Ultimately, point-of-care simultaneous real-time measurements of insulin and blood glucose using biosensor technology can offer significant potential for minimising the impact of the impending diabetes epidemic and improve the quality of life of diabetic patients." (PMID 37504117, 2023). "Zimbabwean adults with diabetes mellitus recruited from an outpatient diabetes clinic at a main referral hospital have been found to have low knowledge about diabetes, in terms of total knowledge, general knowledge and knowledge of insulin use." (PMID 37719056, 2023). "The World Health Organization (WHO) defines diabetes as a multietiological metabolic disorder characterized by chronic hyperglycemia and impaired metabolism of carbohydrates, fats and proteins due to defects in insulin secretion or insulin action or both." (PMID 37153000, 2023). "In addition to improved glycemic control, RT-CGM is associated with reduced rates of emergency department visits and hospitalizations in patients who use insulin as well as reduced diabetes-related distress and hypoglycemic concerns." (PMID 36602920, 2023). "Proper monitoring of glucose and ketone levels, as well as titration of the inhibitor/insulin, may be able to control the incidence of ketoacidosis." (PMID 37762542, 2023). "Their mean duration of diabetes was 18.0 (SD 13.4) years and 173 (77.9%) were insulin dependent." (PMID 37501178, 2023). "Thus, future studies are needed to understand the complex interplay between insulin and dopamine in the progression of nicotine dependence in persons with diabetes." (PMID 38389818, 2023). "Using insulin is one of the most important ways to treat diabetes." (PMID 37828117, 2023).
diabetes (continued). "Of note, the reported rate of > 10% for suicidal thoughts and self-harm, twofold higher in females, is still alarming because, in diabetes, self-harm and (indirect) suicide can also be committed through insulin omission and intentional overdose, although reported suicide rates are low." (PMID 38129890, 2023). "In addition, it increased the expression levels of insulin signaling-related factors in adipose tissues and suppressed type 2 diabetes mellitus." (PMID 36902049, 2023). "By meticulously selecting suitable candidates for beta cell transplantation based on a comprehensive analysis of their diabetes profile, encompassing genetic factors, insulin responsiveness, and other individual parameters, healthcare providers can provide highly personalized therapeutic options." (PMID 37915365, 2023). "Our CRISPR screening approach was successful in identifying robust modulators of insulin content, as shown through the detection of not only the insulin gene itself but also genes involved in monogenic types of diabetes or known regulators of insulin transcription and secretion." (PMID 36543916, 2023). "Considering the common origin of the pancreas and gallbladder together with extrahepatic bile ducts, it is important to know if the porcine biliary tract has endocrine cells producing insulin and glucagon which can contribute to the pathophysiology and treatment of diabetes." (PMID 38094502, 2023). "Telemonitoring of diabetes patients with an insulin pump is used to check the insulin value." (PMID 36978073, 2023). "As a characteristic of obesity and diabetes, insulin resistance also occurs in the brain of AD patients resulting in compromised synaptic and neuronal plasticity, which are usually ameliorated by insulin." (PMID 37508448, 2023). "This review describes the most commonly prescribed non-insulin anti-diabetic drugs for diabetes management, their mechanism of action, and the existing evidence about their effectiveness in improving glycaemic variability and diabetes control." (PMID 38046184, 2023). "Diabetes mellitus is a serious, metabolic disorder that arises from chronic and persistently elevated levels of blood glucose either due to the body’s inability to produce sufficient insulin, or through resistance offered by body tissues to insulin." (PMID 37033637, 2023). "Additionally, for people living with diabetes, access to insulin is often intermittent in LICs, leading to hypoglycaemia and hyperglycaemia." (PMID 36755920, 2023). "Thus, older adult patients with diabetes not only require insulin injections, but also experience a variety of adverse effects that persist throughout their lives and do not improve their HRQOL." (PMID 37570372, 2023). "Alteration of glucose/insulin system, such as in subjects with diabetes, may increase both local synthesis and action of IGF1, leading to glomerular enlargement and progression of diabetic nephropathy." (PMID 37338602, 2023). "The proportion of blood glucose values > 1.8 g/L upon the number of tests performed was higher in Period1 (642 [24.7%]) than in Period2 (493 [22.1%]) (P = 0.032), a finding that was consistent across the patient subsets formed according to the known existence of diabetes and the use of insulin." (PMID 37330419, 2023). "During the five years before the diagnosis, a marked increase in insulin resistance was identified in those that developed T2D with a concomitant initial increase in insulin secretion 3–4 years before the diagnosis, followed by a decrease just before the diabetes diagnosis." (PMID 37432389, 2023). "However, abnormal insulin sensitivity precedes the clinical diagnosis of diabetes by up to 15 years; thus, the mechanisms that form the basis of insulin resistance should be investigated." (PMID 37298118, 2023).
diabetes (continued). "In vivo tests on experimental animals with type 2 diabetes mellitus showed that berberine reduced fasting blood glucose levels and fasting serum insulin levels, increased insulin sensitivity, increased the amount of insulin receptor mRNA, and increased PKC activity in the liver." (PMID 36770960, 2023). "Diabetes mellitus (DM) is caused by higher levels of blood glucose due to the lack of production of insulin by the body, resistance to insulin, or both." (PMID 37090386, 2023). "Diabetes mellitus (DM) is a metabolic disorder majorly arising from the pathophysiology of the pancreas manifested as a decline in the insulin production or the tissue’s resistance to the insulin." (PMID 36770873, 2023). "Overall, some studies suggest that exposure to phthalates may influence glucose- and insulin-related parameters, culminating in the development of diabetes mellitus, from pregnant women to elderly people." (PMID 37367903, 2023). "Diabetes mellitus (DM) type 2 is a chronic, progressive disease, resulting in multiple pathophysiologic defects including insulin resistance, reduced beta cell function, increased hepatic glucose output, inappropriate glucagon secretion, and decreased incretin effect." (PMID 36726134, 2023). "Diabetes is a chronic, metabolic disorder characterized by high blood sugar levels, determined by insufficient production or function of insulin, a hormone produced by the pancreas, which regulates the uptake and metabolism of glucose, the main source of energy for the body’s cells." (PMID 37047748, 2023). "Diabetes, a complex disorder where the body does not produce or properly use insulin, comes with metabolic dysregulations that cause vascular changes." (PMID 37754812, 2023). "Although an insufficient β cell mass is essential for the development of T2DM, it is difficult to accurately measure β cell mass in living people, and insulin secretion capacities widely vary; therefore, β cell mass has limited use as a biomarker for new onset diabetes." (PMID 37974292, 2023). "A rebalancing of the Firmicutes/Bacteroidetes ratio via diet or probiotics could be an important clinical tool to suppress systemic inflammation, improve insulin sensitivity, and limit retinal damage in diabetes." (PMID 37109497, 2023). "Obtaining school glucose and insulin dosing records may be less important with the increasing utilization of diabetes devices." (PMID 37929230, 2023). "In comparison, a definitive prospective study of diabetes remission in 268 consecutive patients with new-onset T1D, mostly adults, reported a rate of 18.3% (median 6 months) for partial remission from insulin therapy and a complete remission rate of 12.3% (median 6 months)." (PMID 37293502, 2023). "The metabolic traits in centenarians are maintaining insulin sensitivity and a lower incidence of diabetes, which suggests that glucose homeostasis may play a crucial role in health and longevity." (PMID 37408986, 2023). "Vaspin has insulin-sensitizing effects, improving insulin tolerance in animal models of diabetes." (PMID 38140318, 2023). "○ Engagement with and access to insulin and glucose data through app on phone (and if and how this changed over time); which of the available data participants used; if/how data access affected how they managed diabetes." (PMID 37795883, 2023). "People with type 1 diabetes mellitus (DM1) cannot naturally regulate their insulin." (PMID 37050725, 2023). "Type 2 diabetes mellitus (DM) results in the human body's inefficient use of insulin." (PMID 37007415, 2023). "The sensitivity of this hydrogel to pH and glucose, on the one hand, and its non-toxicity and biocompatibility, on the other hand, are characteristics that make it a good candidate in the design of a carrier with controlled release of insulin for the treatment of diabetes." (PMID 36771883, 2023). "All type 2 diabetes patients were on oral diabetes medications with 17% also on insulin." (PMID 37316507, 2023).
diabetes (continued). "Indeed, under diabetes conditions, insulin secretory ability is quickly diminished in Japanese subjects." (PMID 37109700, 2023). "In this type of diabetes, cell receptors in the target organs are resistant to insulin and hyperglycemia develops gradually, in other words, at the beginning of the disease, insulin deficiency is relative, however, patients are exposed to macrovascular and microvascular factors." (PMID 38074406, 2023). "Despite reports indicating insulin expression in tissues, such as the brain or liver, the pancreatic β-cells remain the major source of insulin biosynthesis and secretion; therefore, their dysfunction and/or death result in decompensated glucose homeostasis and diabetes development." (PMID 36830593, 2023). "Eating disorders among patients with type 1 diabetes may manifest as the misuse of diabetes medications, i.e., insulin." (PMID 36793059, 2023). "If non-insulin medication has failed, type 2 diabetes mellitus (T2D) patients may need insulin injections to control hyperglycemia to recommended levels." (PMID 37654567, 2023). "Olive oil, nuts, and seeds from plant-based diets are rich in monounsaturated fatty acids (MUFAs) and polyunsaturated fatty acids (PUFAs), which may be responsible for improvements in glucose metabolism, insulin sensitivity, lipids, and CVD risk in diabetics." (PMID 37221569, 2023). "This helps to explore the influence of insulin signaling pathways on the pathogenesis of diabetes." (PMID 36749274, 2023). "All but insulin dose and duration of diabetes remained significant in the parsimonious model." (PMID 37929231, 2023). "Reports showed that they could not only improve the vasodilatation but also modulate insulin sensitivity, therefore being regarded as a potential therapeutic target for diabetes and ischemic cardiomyopathy." (PMID 37297423, 2023). "Similarly, a study into the 25, 50, and 100 mg/kg/day doses of hesperidin reported its positive dose-dependent effects on blood glucose and insulin levels in rats with diabetes mellitus." (PMID 37082190, 2023). "The main types of DM are two; Type 1 diabetes mellitus, which has autoimmune origins, as a result of the destruction of β-cells in the pancreas, leading to defects in insulin production and Type 2 diabetes mellitus, which occurs in adults as a result of insulin resistance or inadequate production." (PMID 37794107, 2023). "It has been suggested that regular assessment of the family's psychosocial needs, and subsequent interventions addressing potential challenges, may be as important to diabetes management as insulin, diet, and physical activity." (PMID 40303260, 2023). "Indeed, Verrucomicrobia and Actinobacteria can increase IL-22 production (an anti-inflammatory cytokine) known to restore insulin sensitivity and alleviate diabetes." (PMID 37764662, 2023). "Current management of people with type 1 diabetes mellitus (T1DM) on intensive insulin therapy recognizes carbohydrates as the most important determinant of postprandial glycaemia; hence, worldwide guidelines recommend carbohydrates counting for determining pre-prandial insulin doses." (PMID 38057844, 2023). "Later studies on the role of inflammation in diabetes revealed that this hypoglycemic action was related to the inhibition of serine kinase IkappaB kinase-beta (IKKbeta), which correlates with the post-receptor action of insulin." (PMID 37298118, 2023). "Our study reveals the role of GIV in insulin secretion and identifies novel signaling machinery regulating glucose-stimulated insulin secretion, which may be a potential target for the therapy of diabetic mellitus." (PMID 36822326, 2023). "The reasons behind this might be due to fact that some anti-diabetes medications (insulin and sulfonylureas and glitazones) promote weight gain and certain anti-hypertensives actually increase insulin resistance." (PMID 37228052, 2023).